CRY1 (cryptochrome circadian regulator 1)
Diseases named in the same sentence as CRY1 in open-access papers (continued):
Sharing a sentence is not in itself a finding about the gene and the disease.
depression (19 papers, 2013 to 2025). "Severity of depression was significantly associated with more methylation of clock genes CRY1 (p = 0.034, R2 = 0.16) and CRY2 (p = 0.019, R2 = 0.47)." (PMID 33809270, 2021). "With the focus on the cryptochrome genes, earlier studies have indicated CRY1 genetic variants in major depressive disorder and CRY2 genetic variants in seasonal affective disorder, winter depression in particular, and in bipolar type 1 disorder." (PMID 23951166, 2013). "In other studies, CRY1 is robustly associated with depression." (PMID 38132358, 2023). "Several circadian genes were upregulated, including CLOCK, ARNTL, CRY1, DBP, and NR1D1; with associations found between CLOCK and lower state anxiety at baseline, and between CRY2 and higher self-esteem and lower depression at baseline (p < 0.05)." (PMID 41383341, 2025). "Cryptochrome 1 (CRY1) variant rs2287161, which has been associated with the regulation of circadian rhythms and linked to depression and sleep disturbance, also modifies the CHO effect on glycaemic indices." (PMID 33503923, 2021). "Specifically, Cry1−/− mice have increased depression-like behavior, Cry2−/− mice have reduced sucrose preference, and Cry1−/−;Cry2−/− double knock-out mice have increased anxiety-like behavior." (PMID 29230328, 2017). "Of them, NR1D1 genetic variants have been demonstrated to associate with bipolar disorders and depressive disorders, CRY2 (cryptochrome 2) with depressive disorders and bipolar disorders, and CRY1 (cryptochrome 1) with depressive disorders." (PMID 25610405, 2014). "On the other hand, CRY1 and NPAS2 appeared to be associated to major depression disorder." (PMID 36833279, 2023). "Here, we observed that the effects of CRY1, PER3-VNTR, and ZBTB20 were also directly associated with depression, underscoring the possibility that these genes directly impact mood regulation via transcriptional (CRY1, PER3-VNTR) or activational (ZBTB20) regulatory mechanisms." (PMID 38132358, 2023). "Moreover, the assessment of clock gene expression in the hippocampus, a brain region involved in AD and depression, revealed altered levels of cry1, dec2, and rev-erb-beta in IL-6 KO mice." (PMID 28382017, 2017). "A single CRY1 variant has been associated with major depressive disorder earlier but there is no replication of the finding." (PMID 23951166, 2013). "Transgenic animal models of clock disruptions such as PER1Brdm1−/−, CRY1−/−, and CRY2−/− mutant mice displayed evident depression or anxiety-like behaviors, as well as arrhythmic feeding behavior and impaired glucose tolerance." (PMID 29740382, 2018). "In contrast, Cry1-KO mice were reported to show an increase or no change in depression-like behaviors in different studies, although reduced anxiety-like behaviors were also reported in these mice." (PMID 37606043, 2023). "Given this overlap, we utilized patient depression scores (BDI) as the outcome for ARACNE analysis to test the hypothesis that PER3-VNTR, CRY1, and ZBTB20 are directly involved in mood regulation." (PMID 38132358, 2023). "Concerning PD depression, it has been indicated that TEF rs738499, but not CRY1 rs2287161 or CRY2 rs10838524 gene polymorphisms, were linked to depressive symptoms among PD patients in the Chinese population." (PMID 37374342, 2023). "TEF, CRY1, and CRY2 gene polymorphisms have been associated with depression risk in non-PD individuals." (PMID 37374342, 2023). "Indeed, while one study showed that Cry1 or Cry2 single-KO and Cry1/2 double-KO mice showed increased anxiety states, but not depression-like behaviors, another study reported Cry1/2 double-KO displayed increased anhedonia compared to WT mice." (PMID 37441675, 2023). "Our findings revealed that the lack of Cry1 and Cry2 genes (Cry1−/−Cry2−/−) elicits cognitive dysfunction, promotes anxiety-related behavior and results in a decreased sensitivity to cocaine but does not affect depression-like behavior." (PMID 24187535, 2013).
depression (continued). "Interestingly, protective effects of CRY1-GG, PER3-VNTR-4,5, and ZBTB20 genotypes on seasonality and depression were not mediated by chronotype, suggesting some clock variants have direct effects on depressive symptoms related to SAD." (PMID 38132358, 2023).
Anxiety (18 papers, 2010 to 2025). Intense feelings of nervousness, tension, or panic often arise in response to interpersonal stresses. "The association of CRY1/PER3-A variant genotypes with severe anxiety in females was partially mediated by extreme evening chronotype." (PMID 38102312, 2023). "In the overall dataset, the combination of PER3B-AG and CRY1-CG was most strongly associated with the risk of having anxiety symptoms (OR 15.3, p = 0.026)." (PMID 35365695, 2022). "We found that the combination of PER3B-AG and CRY1-CG was most strongly associated with the risk of having anxiety symptoms." (PMID 35365695, 2022). "In our study, we observed a higher expression of the CRY1 gene in subjects with low levels of state anxiety." (PMID 41383341, 2025). "A study on mouse models has shown that inhibition of cyr1/2 (Cry1−/−Cry2+/+ and Cry1+/+Cry2−/−) impairs recognition memory and elevates anxiety." (PMID 36979479, 2023). "In females, the CRY2/ZBTB20 genotype combination showed a > 200-fold increase in odds of anxiety and PER3/ZBTB20 and CRY1 /PER3-A genotype combinations also appeared as female risk factors." (PMID 38102312, 2023). "For their influence on brain development, genetic variations of circadian genes (e.g., CRY1, CLOCK, and NPAS2) are oftentimes associated psychiatric disorders such as anxiety, mood disorders, and alcohol use." (PMID 36833279, 2023). "In cryptochrome circadian regulator 1/2(Cry1/2) knockout mice, elevated anxiety levels are observed compared to those in wild-type mice." (PMID 36699021, 2022). "All other variants (PER2, PER3 VNTR, PER3A, CLOCK3111, CRY1, and CRY2 SNPs) were directly associated with anxiety symptoms following bootstrap analysis." (PMID 35365695, 2022). "Similarly, mice with deletions in Cry1, Cry2 or both, displayed changes in anxiety; however, despair-related behaviour was unaffected." (PMID 40092590, 2025). "Altogether, these findings suggest that the modulation of CRY1 expression may lead to alterations in sex-specific mood pathways and diurnal preference pathways in ways that are conducive to anxiety in females." (PMID 38102312, 2023). "In males, CRY1/PER3-A and PER3-B/ZBTB20 genotype combinations were associated with anxiety risk." (PMID 38102312, 2023). "Interestingly, studies find mixed outcomes of a global Cry1 knockout on anxiety-like behaviors in mice." (PMID 35755440, 2022). "Motor impairment in the rotarod task has been demonstrated in global Cry1/Cry2 knockout mice, and the authors argued that it may be a consequence of elevated anxiety-like behavior observed in those animals." (PMID 35755440, 2022). "In addition, scientists have found that melatonin receptor agonists relieved patients’ depression and anxiety with decreased Per1, Per2, Cry1, Cry2 and Nr1d1 expression." (PMID 36699021, 2022). "However, the number of open arm entries and time spent in the open arms of the elevated plus maze were significantly lower compared to WT mice in Cry1−/−Cry2+/+ and in Cry1+/+Cry2−/− mice suggesting that cryptochromes influence anxiety-related behaviors." (PMID 24187535, 2013). "This is in line with the observation that Afterhours mutant mice showed lower anxiety-related behaviors and suggests largely complementary roles of Cry1 and Cry2 with an opposite influence of the circadian transcriptional activators and repressors on anxiety-related behavior." (PMID 24187535, 2013). "Thus, hyperactive Bmal1-/-demonstrated "normal" level of anxiety, while both hyperactive Clock/Clockand hypoactive Cry1,2-/- had decreased level of anxiety." (PMID 20519775, 2010). "Moreover, we further observed elevated anxiety in Cry1−/−Cry2+/+ and Cry1+/+Cry2−/− mice." (PMID 24187535, 2013). "Specifically, CRY1 and CRY2 knockout mice have been demonstrated to display increased anxiety-related behavior." (PMID 38094940, 2023).
Anxiety (continued). "Average anxiety scores for individuals with PER3B-AG and CRY1-CG genotypes were higher (males: 54.8 ± 4.1; females: 46.7 ± 2.5) than for individuals of other genotypes (males: 41.3 ± 0.8, females: 44.8 ± 0.6)." (PMID 35365695, 2022). "Interestingly, cognitive function and anxiety-related behaviors but none of the other behavioral parameters were also altered in mice lacking either Cry1 or Cry2." (PMID 24187535, 2013). "Cry1 or Cry2 single knockout mice showed elevated anxiety in the elevated plus maze, but less prominent compared to mice lacking both Cry1 and Cry2 that displayed robust anxiety-related behaviors across tests." (PMID 24187535, 2013).
breast carcinoma (18 papers, 2013 to 2025). "CRY1-mediated decrease of Pdk1 expression can also be observed in a breast cancer cell line MDA-MB-231, whose glycolysis is associated with Pdk1 expression." (PMID 38199564, 2024). "In conclusion, our findings suggested that DNA hypomethylation in certain CpG sites of CRY1 may be part of a causal pathway between road traffic noise and risk of breast cancer." (PMID 39587706, 2024). "However, among breast cancer cases, road traffic noise tended to be more strongly associated with lower methylation in CRY1 CpG1, CpG2, CpG4, CpG6, and CpG12, with betas ranging from -0.30 to -0.19." (PMID 39587706, 2024). "Other cryptochrome gene variants have previously been shown to be associated with a decreased breast cancer risk including GT genotype of rs1056560 in CRY1 (OR = 0.84 95% CI = 0.71–0.99) and CC genotype of rs1401417 in CRY2 (OR = 0.24 95% CI = 0.08–0.73) in premenopausal women." (PMID 31739444, 2019). "Nevertheless, in CRY1 CpG2 and CpG5 and in CLOCK CpG1 increasing levels of methylation tended to be associated with lower odds of breast cancer (OR 0.88; 95% CI 0.76–1.02, OR 0.84; 95% CI 0.74–0.96, and OR 0.80; 95% CI: 0.68–0.94, respectively)." (PMID 39587706, 2024). "We observed some indication that methylation of multiple CpGs in CRY1 and CLOCK was inversely associated with breast cancer." (PMID 39587706, 2024). "CRY1’s role in breast cancer development is not fully understood; however, CRY is involved in regulation of DNA replication, DNA damage, and cell cycle." (PMID 39587706, 2024). "A systematical analysis of genomic profiling and clinical data showed significantly decreased Cry1 and Cry2 mRNA levels in multiple cancer types, including breast carcinoma, lung squamous cell carcinoma, thyroid carcinoma, and lung adenocarcinoma." (PMID 37024472, 2023). "Altered Cry2 expression, however, is more likely to be associated with altered activity of established oncogenic or tumor suppressor pathways in breast cancer than Cry1." (PMID 37024472, 2023). "Comparing breast cancer to adjacent tissue, PER1, PER2, PER3, and CRY2 levels are decreased; CLOCK is increased; and CRY1 downregulation was found to escalate directly with breast cancer stage." (PMID 35163264, 2022). "In terms of genetic predisposition, logistic regression analyses have linked different CLOCK, CRY1, and PER2 genotypes to breast cancer risk, and several studies have implicated specific single-nucleotide polymorphisms." (PMID 35163264, 2022). "Studies have found that mutations in BMAL1, CRY1, and CRY2 are often associated with a higher risk and recurrence of acute myeloid leukemia and endometrial, ovarian, colorectal, and breast cancers." (PMID 34149816, 2021). "There are a few studies which focus on CRY1 and CRY2 polymorphism, but there are some significant gene variants associated with breast cancer risk." (PMID 31739444, 2019). "The key circadian genes, PERIOD 2 (PER2 variant 2), CLOCK, TIMELESS, CRYPTOCHROME 1 (CRY1) and CRYPTOCHROME 2 (CRY2) were all also significantly expressed in all breast cancer cell lines and all patients’ breast cancer tissues examined." (PMID 24683528, 2013). "In summary, our data suggest that DNA hypomethylation in CRY1 and BMAL1 could be part of a causal chain from road traffic noise to breast cancer." (PMID 39587706, 2024). "In CRY1 CpG2 and CpG5 and in CLOCK CpG1, increasing levels of methylation tended to be associated with lower odds of breast cancer, with odds ratios (OR) of 0.88 (95% confidence interval (CI) 0.76–1.02), 0.84 (95% CI 0.74–0.96), and 0.80 (95% CI 0.68–0.94), respectively." (PMID 39587706, 2024). "In a study of nurses with breast cancer, exposure to night work was associated with increased methylation of the CLOCK, BMAL1, PER1 and CRY1 genes, compared with controls, suggesting that epigenetic regulation of these clock genes may have a role in breast cancers linked to shift workers." (PMID 33089179, 2019).
breast carcinoma (continued). "In post hoc analyses, we evaluated the effect of categorized methylation in CRY1 (CpG1, CpG2, CpG4, CpG6, CpG12) and BMAL1 (CpG2, CpG6, CpG7) and breast cancer." (PMID 39587706, 2024). "We also performed experiments using another breast cancer cell line, MCF-7, to analyze the correlation between CRY1 and PDK1 proteins." (PMID 38199564, 2024). "We recently reported that in spite of their failure to express the tumor suppressor and clock gene Per2, our tissue-isolated human breast cancer xenografts exhibit daily oscillations in the expression of Clock, Cry1 and Bmal1 that were disrupted in the absence of a circadian melatonin signal." (PMID 25099274, 2014).
diabetes (16 papers, 2012 to 2025). "The interaction between the cryptochrome 1 (CRY1) rs2287161 G>C variant and several diabetes-related traits (fasting glucose and insulin, HOMA-IR and QUICKI index) has been studied in The Mediterranean and North American Cohort." (PMID 28574454, 2017). "In the present study, B12 modulated several core clock genes (Bmal1, Cry1, Cry2, Per1, Per3), while other genes were primarily affected by diabetes (Bhlhe40, Hif3a, and Nr1d1)." (PMID 41463345, 2025). "We found significantly reduced CRY1 mRNA levels in older diabetes participants (>50 years old) vs healthy participants in the same age group (p<0.01)." (PMID 38981930, 2024). "Previous studies found that DDB1-mediated degradation of Cry1 was an important target for insulin action on glucose homeostasis, and the FUT8 was strongly associated with increased susceptibility to diabetes." (PMID 36360309, 2022). "Diabetes downregulated Clock, Bmal1, and Per2 expression, upregulated Cry1 and Rev-erbα expression, reduced corneal epithelial mitosis, and increased leukocyte (neutrophils and γδ T-cells) recruitment to the cornea." (PMID 27611469, 2016). "In this study, we show that diabetes influenced the circadian rhythm in the expression of five core clock genes (Clock, Bmal1, Per2, Cry1, and Rev-erbα), as well as mitosis, in the normal murine corneal epithelium." (PMID 27611469, 2016). "Individuals with the CRY1 variant exhibit increased insulin resistance and diabetes risk compared with those without the CRY1 variant." (PMID 39165284, 2024). "Diabetes alters the circadian rhythm of the corneal epithelium in mice, such that the expression of Clock, Bmal1, and Per2 is downregulated, and the expression of Cry1 and Rev-erbα is upregulated." (PMID 39062510, 2024). "Diabetes altered the circadian rhythm of the corneal epithelium in mice, such that the expression of Clock, Bmal1, and Per2 was downregulated, and the expression of Cry1 and Rev-erbα was upregulated." (PMID 27611469, 2016). "The role of CRY1 in human diabetes may therefore warrant further investigation." (PMID 22485135, 2012). "The other study analyzed the interaction between the cryptochrome 1 (Photolyase-Like) (CRY1) rs2287161 SNP and 4 diabetes-related traits (fasting glucose and insulin, HOMA-IR index and QUICKI index)." (PMID 25421534, 2014). "A list of 15 known clock genes from the primary (Arntl, Clock, Npas2, Per1, Per2, Per3, Cry1, Cry2), secondary (Nrd1d1, Nr1d2, Rora, Rorb, Rorc), and accessory TTFL loops (Nfil3, Dbp) were selected to investigate the effect of diabetes on their rhythmic expression." (PMID 38039846, 2024).
prostate carcinoma (16 papers, 2012 to 2026). A carcinoma that arises from epithelial cells of the prostate gland. "CRY1, a circadian rhythm regulator, is also implicated in DNA repair and tumorigenesis in cancers such as prostate cancer, making it a potential therapeutic target in Group 3 MB." (PMID 40002179, 2025). "Key findings demonstrate that CRY1 expression is androgen-responsive and associates with poor outcome in prostate cancer." (PMID 33452241, 2021). "Besides, cry1 expression is androgen responsive, Cry1 regulates DNA repair and the G2/M transition and it is associated with poor outcome in prostate cancer and colorectal cancer." (PMID 35216153, 2022). "Cry1 functions as a tumor-specific regulator of DNA repair, controlling the G2/M transition in prostate cancer." (PMID 41142939, 2025). "A reduction in the expression of circadian genes, including CLOCK, CRY1, CRY2, PER2, and BMAL1, has been associated with an increased risk of prostate cancer." (PMID 39062777, 2024). "In particular, CRY1, CRY2, ROR, and BMAL1 have been implicated in the progression of prostate cancer." (PMID 39062777, 2024). "Similar to CRY1 in prostate cancer cells, polyQ-expanded AR bound AREs present in the promoters of Lsd1 and Prmt6 in SBMA myotubes." (PMID 36746939, 2023). "Eight of these, located in four genes, NPAS2 (2 SNPs), CSNK1E (3 SNPs), CRY1 (2 SNPs), and CRY2 (1 SNP), were significantly associated with prostate cancer risk." (PMID 30518396, 2018). "Notably, dysregulation of certain CCCGs, including multiple genomic variants of CRY1/2, CSNK1E, and NPAS2, is shown to be associated with an increased risk of prostate cancer." (PMID 40948103, 2026). "Furthermore, the CRY1 gene has been identified as a pro‐tumorigenic and hormone‐induced factor in mCRPC patients, with a characterized role in DNA repair in prostate cancer tumors." (PMID 40948103, 2026). "Findings showed that all core circadian rhythm gene pathways, except CRY1 (rs7297614 and rs1921126), were not correlated with prostate cancer risk." (PMID 39011396, 2024). "This study was specifically carried out in human prostate cancer cell lines as well as tissues from prostate cancer patients, and further studies are needed to define the role of CRY1 in regulation of DNA repair genes in other tissues, particularly those that are not hormone responsive." (PMID 39282509, 2023). "In contrast, our results showed that Cry1 arrested the HCC cell cycle at the G1 phase, possibly due to the context-dependent role in HCC versus prostate cancer." (PMID 41142939, 2025).